WDR90 (WD repeat domain 90)
Description:
Microtubule-binding protein that plays a crucial role in ensuring inner core protein localization within the centriole core, as well as in maintaining the microtubule wall integrity and the overall centriole roundness and stability. Required for efficient primary cilium formation.
Synonyms: C16orf15; C16orf16; C16orf17; C16orf18; C16orf19; KIAA1924; FLJ36483; POC16
Tractability: Antibody: its Gene Ontology location is reachable by antibodies, with high confidence. PROTAC: ubiquitination databases record sites on it.
Gene: Protein-coding gene on chromosome 16 (649,287 to 667,837, forward strand). Ensembl gene ENSG00000161996.
Subcellular location: Cytoplasm, cytoskeleton, microtubule organizing center, centrosome, centriole; Cytoplasm, cytoskeleton, microtubule organizing center, centrosome, centriolar satellite
Subcellular location (Human Protein Atlas): Basal body; Centrosome; Plasma membrane
Gene Ontology:
Molecular function: microtubule binding; protein binding
Biological process: centriole elongation; cilium assembly
Cellular component: centriolar satellite; centriole; centrosome; ciliary basal body; cilium; cytoskeleton
Genetic constraint (gnomAD): Loss-of-function variants: 238 observed, 178.9 expected, observed/expected ratio (o/e) 1.33, 90% interval 1.2 to 1.48. The synonymous counts are far from expectation, so gnomAD's model fits this gene poorly and the ratio says little. Missense variants: 2,731 observed, 2,284.5 expected, observed/expected ratio (o/e) 1.2, 90% interval 1.16 to 1.23. Synonymous variants: 1,263 observed, 992.27 expected, observed/expected ratio (o/e) 1.27, 90% interval 1.21 to 1.33.
Homologues: Orthologues: chimpanzee WDR90 (99% identical), mouse Wdr90 (72% identical), guinea pig WDR90 (70% identical), pig WDR90 (68% identical), dog WDR90 (66% identical), tropical clawed frog wdr90 (55% identical), zebrafish wdr90 (48% identical). Paralogues in human: EML5 (12% identical), EML6 (12% identical), EML3 (11% identical), EML4 (11% identical), EML1 (10% identical), EML2 (10% identical), CFAP44 (10% identical), CFAP251 (8% identical), CFAP52 (7% identical).
Diseases named in the same sentence as WDR90 in open-access papers:
WDR90 is named in the same sentence as 5 diseases in open-access papers, as found by Europe PMC text mining. Sharing a sentence is not in itself a finding about the gene and the disease. The quoted sentences say what the papers report.
Chronic pain (1 paper, 2025). Persistent pain, usually defined as pain that has lasted longer than 3 to 6 months. "Among the 42 new chronic pain loci that harbor protein-coding variants, five genes (HECTD3 (chr1.p34.3), CCDC17 (chr1.p34.3), DNM1 (chr9.q33.1), PCDHA1 (chr5.q31.5), and WDR90 (chr16.p13.3)) showed evidence of colocalization in more than one brain tissue." (PMID 40297705, 2025).
WDR90 also shares sentences with these, for which no sentence is quoted: Azoospermia (1 paper); breast carcinoma (1); ciliopathy (1); insomnia (1).